MT-ND5 (mitochondrially encoded NADH:ubiquinone oxidoreductase core subunit 5)
Description:
Core subunit of the mitochondrial membrane respiratory chain NADH dehydrogenase (Complex I) which catalyzes electron transfer from NADH through the respiratory chain, using ubiquinone as an electron acceptor. Essential for the catalytic activity and assembly of complex I.
Synonyms: ND5; NAD5; formerly MTND5
Tractability: Small molecule: an approved drug acts on it; a structure with a bound ligand is known. Antibody: UniProt predicts a signal peptide or a membrane-spanning region.
Gene: Protein-coding gene on chromosome MT (12,337 to 14,148, forward strand). Ensembl gene ENSG00000198786.
Subcellular location: Mitochondrion inner membrane
Pathways (Reactome):
Metabolism: Complex I biogenesis; Respiratory electron transport
Metabolism of proteins: Mitochondrial protein degradation; Mitochondrial translation termination
Gene Ontology:
Molecular function: NADH dehydrogenase (ubiquinone) activity
Biological process: mitochondrial electron transport, NADH to ubiquinone; mitochondrial respiratory chain complex I assembly; aerobic respiration; electron transport coupled proton transport; proton motive force-driven mitochondrial ATP synthesis; ATP synthesis coupled electron transport; response to hydrogen peroxide; response to hypoxia
Cellular component: mitochondrial inner membrane; mitochondrion; respiratory chain complex I
Gene-disease validity (ClinGen):
ClinGen rates the evidence that MT-ND5 causes each of these diseases.
Leigh syndrome (mitochondrial): Definitive. A progressive neurological disease defined by specific neuropathological features associating brainstem and basal ganglia lesions.
mitochondrial disease (mitochondrial): Definitive.
Homologues: Orthologues: chimpanzee MT-ND5 (93% identical), macaque ND5 (77% identical), pig ND5 (70% identical), rabbit MT-ND5 (69% identical), guinea pig ND5 (67% identical), mouse mt-Nd5 (64% identical), rat Mt-nd5 (63% identical), tropical clawed frog ND5 (57% identical), zebrafish mt-nd5 (54% identical), Drosophila melanogaster mt:ND5 (33% identical), Caenorhabditis elegans WBGene00010967 (25% identical). Paralogues in human: MT-ND4 (14% identical), MT-ND2 (12% identical).
Diseases named in the same sentence as MT-ND5 in open-access papers:
MT-ND5 is named in the same sentence as 133 diseases in open-access papers, as found by Europe PMC text mining. Sharing a sentence is not in itself a finding about the gene and the disease. The quoted sentences say what the papers report.
MELAS (27 papers, 2009 to 2026). "MT-ND5 mutation manifesting as MELAS in association with nephropathy is much less recognized with only nine such cases reported so far." (PMID 39262552, 2024). "The most common mutation associated with MELAS is related to pathogenic variants of the MT-TL1 gene (>80%) whereas MT-ND5 contributes to only less than a tenth of these cases." (PMID 39262552, 2024). "Of note, the MT-ND5 mutation is associated with a broader mitochondrial disease spectrum, but it also exhibits MELAS-like characteristics such as SLEs and progressive encephalopathy." (PMID 39766231, 2024). "This is just the second instance of MELAS secondary to the pathogenic novel m.13091T>C variant of MT-ND5." (PMID 39262552, 2024). "Mitochondrial cytopathies, predominantly MT-TL1 mutations and, to a lesser extent, MT-ND5, have been associated with mitochondrial encephalomyopathy with lactic acidosis and stroke-like episodes (MELAS), manifesting as multi-organ dysfunction." (PMID 39262552, 2024). "All four patients with mutations in MT-ND1 or MT-ND3 had LS, whereas patients with MT-ND5 mutations presented equally often with LS or MELAS." (PMID 31996177, 2020). "Of note, the m.13565C>T MT-ND5 mutation studied here was originally isolated from a MELAS patient who also carries a mutation in POLG, which encodes the catalytic subunit of the mitochondrial DNA polymerase." (PMID 27110715, 2016). "Moreover, MT-ND5 mutations can rarely cause adult-onset nephropathy, either isolated or associated with MELAS and presenting either as FSGS or tubulo-interstitial disease." (PMID 39262552, 2024). "Heteroplasmic variants in MT-ND5 have previously been identified in MELAS patients or Leigh syndrome and there have been some theories that this may be a novel hot spot for MELAS causing variants outside of the classical m.3243A > G variant." (PMID 35699875, 2022). "In addition, it is worth emphasizing the important role of MTND mutation, especially the MT-ND5 gene in the diagnostic workup of patients presenting with MELAS/LS overlap syndrome." (PMID 34025555, 2021). "Furthermore, severe clinical phenotypes associated with a relatively low mutant load have also been observed in other common point mutations in the MT-ND5 gene, including the m.13513G > A mutation, where a mutant load of <50% in muscle has been reported in association with LS and MELAS." (PMID 29506874, 2018). "Human m.G3376A (mouse m.G2820A) and m.G13513A (mouse m.G12918) mutations affect the coding region of MT-ND1 and MT-ND5 genes, respectively, which associated with LHON and MELAS." (PMID 39856740, 2025). "The common MT-ND5 m.13513G > A mutation is linked to multiple syndromes, including LS, MELAS, MERRF, LHON, and MELAS-LS overlap syndrome." (PMID 39850733, 2024). "Among patients with MELAS, 13/14 had a mutation in MT-TL1 (m.3243A>G in 12 and 1 with m.3251A>G) and 1 in MT-ND5." (PMID 38434220, 2024). "The m.13513G>A mutation, one of the most frequently reported mutations in the MT-ND5 gene of mtDNA, has been described with various phenotypes, including MELAS, LS, and overlap syndromes including LHON/MELAS, MELAS/CPEO, and MELAS/LS." (PMID 34025555, 2021). "Among these, m.13513G>A in the MT-ND5 gene has been recognized in 10–15% of MELAS cases." (PMID 39766231, 2024). "Interestingly, mtND5 variants have been extensively studied and found to cause several mitochondrial diseases including LHON, adult encephalopathy, MELAS, and Leigh syndrome." (PMID 37544976, 2023). "For example, about 80% of patients with MELAS harbor the m.3243A>G mutation in the mitochondrial tRNALeu(UUR) gene (MTTL1), whereas mutations in polypeptide-coding genes, including subunits 1, 5, and 6 of complex I (MT-ND1, MT-ND5, and MT-ND6), have also been identified in MELAS." (PMID 34025555, 2021).
Leigh syndrome (24 papers, 2012 to 2026). "Genetic testing using next-generation sequencing of mitochondrial DNA identified a pathogenic variant in MT-ND5 (m.13513G>A) with 95% heteroplasmy, confirming the diagnosis of mitochondrial DNA-associated Leigh syndrome." (PMID 41357011, 2025). "This case illustrates the devastating neonatal presentation of Leigh syndrome with characteristic neuroimaging findings and confirmed MT-ND5 mutation." (PMID 41357011, 2025). "Genetic testing identified a 95% heteroplasmic pathogenic variant in MT-ND5, confirming mitochondrial DNA-associated Leigh syndrome." (PMID 41357011, 2025). "Little is known about changes in gene expression levels, associated with Leigh syndrome, and in particular with the m.13513G>A variant in the MT-ND5 gene." (PMID 36975485, 2023). "Induced pluripotent stem (iPS) neurons with the m.13513G > A mutation in the MT-ND5 gene, which leads to respiratory chain deficiency and is associated with Leigh syndrome, have decreased calcium buffering capability, as shown in electrophysiological research." (PMID 36831068, 2023). "We describe a patient with Leigh syndrome caused by a pathogenic variant in the MT-ND5 gene (MIM# 516005) designated as m.13513G > A;p.Asp393Asn with a heteroplasmy of 69%." (PMID 36855210, 2023). "A combined mitochondrial genome and mitochondrial nuclear gene panel revealed a pathogenic variant in the MT-ND5 gene, designated as m.13513G > A;p.Asp393Asn with heteroplasmy of 69%, confirming the diagnosis of Leigh syndrome." (PMID 36855210, 2023). "A previous report from our laboratory described a patient with Leigh syndrome harboring the mtDNA variant m.13513G>A in the MT-ND5 gene at 60% heteroplasmy level." (PMID 36975485, 2023). "This association between catecholamine induced autonomic dysfunction and Leigh syndrome has been previously reported only once with MT-ND5 mutation." (PMID 36855210, 2023). "MT‐ATP6 deficiency caused by m.8993T>G mutation and MT‐ND5 deficiency induced a severe form of Leigh syndrome." (PMID 31967322, 2020). "Patient A was a female child with Pearson’s syndrome caused by a ~6.0 kb single, large-scale mtDNA deletion; Patient B was a female child with Complex-I deficient Leigh syndrome and a heteroplasmic m.13514 A > G, p.(Asp393Gly) MTND5 mutation." (PMID 29379065, 2018). "The m.13094T>C mutation in MT-ND5 was considered a rare cause of mitochondrial disease that had been previously reported in association with Leigh Syndrome only." (PMID 29506874, 2018).
breast cancer (11 papers, 2013 to 2025). A primary or metastatic malignant neoplasm involving the breast. "Although variants were distributed throughout the entire mtDNA, the genes MT-ND5 (p = 0.011), tRNA (p = 0.022), and rRNA (p = 0.045) were significantly more mutated in patients with breast cancer in comparison to healthy women." (PMID 40943376, 2025). "Another J haplogroup-defining SNP, m13708G>A (MT-ND5, ALA-THR), has also been associated with breast cancer." (PMID 31380278, 2019).
mitochondrial encephalomyopathy (6 papers, 2009 to 2025). A heterogenous group of disorders characterized by alterations of mitochondrial metabolism that result in muscle and nervous system dysfunction. "Mutations that disrupt the ability of oxidative phosphorylation to meet these metabolic demands, such as those observed in the MT-ND5 gene, are important causes of morbidity in childhood mitochondrial encephalomyopathies." (PMID 41523412, 2025).
COVID-19 (5 papers, 2021 to 2024). A disease caused by infection with severe acute respiratory syndrome coronavirus 2. "Chi Square analysis of corrected observation frequency indicated that cytochrome complex members including CYB, CYTB, CYP, CYBR, MT-COX, NDUF, MT-ND5 and other structurally or functionally related proteins were significantly elevated (χ2 ≥ 21, DF = 1, p ≤ 0.0001) in COVID-19 plasma." (PMID 37031181, 2023). "Down regulation of MT-ND1 and MT-ND5 protein coding genes might, at least in part, explain the mitochondrial dysfunction seen in platelets of COVID-19 patients." (PMID 35421970, 2022). "The experiments discovered components of the cytochrome electron transport system including CYCB, CYTB, CYC, CYP, MT-ND5 and MT-COX that were increased in the plasma of COVID-19 patients compared to normal controls." (PMID 37031181, 2023).
hepatocellular carcinoma (5 papers, 2012 to 2024). A malignant tumor that arises from hepatocytes. "Additionally, 10810 (MT-ND4), 12705 (MT-ND5) and 16527 (D-loop) are also shared by the same cancer types (hepatocellular carcinoma and renal cell carcinoma)." (PMID 35183124, 2022).
lung carcinoma (5 papers, 2008 to 2025). "Nonetheless, it has been reported in lung carcinomas that the MT-ND5 gene is also highly mutated." (PMID 40943376, 2025).
Alzheimer disease (3 papers, 2018 to 2026). A progressive, neurodegenerative disease characterized by loss of function and death of nerve cells in several areas of the brain leading to loss of cognitive function such as memory and language. "This SNP causes a synonymous change in MT‐ND5, but is a variant (rs2853499) encoding a non‐synonymous D47N mutation in the microprotein SHMOOSE that has been associated with an increased risk of Alzheimer's Disease and increased brain atrophy of medial temporal regions in European subjects." (PMID 41432549, 2026).
cardiomyopathy (3 papers, 2013 to 2022). A disease of the heart muscle or myocardium proper. "It was reported that the mutation of MTND5 is associated with cardiomyopathy, which exhibits impairment of mitochondrial complex I assemble, decrease of coupling respiration and adenosine triphosphate (ATP) generation." (PMID 35372351, 2022). "Mutation G13513A (MT-ND5 gene) is believed to be associated with hereditary encephalomyopathy, cardiomyopathy, and the WPW syndrome." (PMID 23874496, 2013).
depression (3 papers, 2018 to 2023). "In addition, 4 mtDNA variants were detected to interact with CRP for both anxiety and depression, including m.12633C>A(MT-ND5), m.9899T>C(MT-CO3), m.4561T>C(MT-ND2), m.11377G>A(MT-ND4)." (PMID 37344456, 2023).
epilepsy (3 papers, 2019 to 2025). A brain disorder characterized by episodes of abnormally increased neuronal discharge resulting in transient episodes of sensory or motor neurological dysfunction, or psychic dysfunction. "The MTND5 gene, which encodes a subunit of mitochondrial complex I, appears to be a hotspot for mutations that lead to epilepsy." (PMID 40659031, 2025). "Other mitochondrial proteins with epilepsy backgrounds that were observed more often in the IE group included MT-CYB and MT-ND5." (PMID 32823271, 2020).
leprosy (3 papers, 2013 to 2024). Leprosy is a chronic infectious disease affecting primarily the skin and peripheral nervous system. "Furthermore, we identified 26 heteroplasmic variants shared between the T and L poles that are present in the MT-RNR2, MT-ND1, MT-ND5, MT-CYB, MT-CO2 and MT-CO3 genes, suggesting that these genes may be correlated with the susceptibility and severity of leprosy." (PMID 38062538, 2023). "Notably, six variants were exclusively found in both clinical poles of leprosy, including m.4158A>G and m.4248T>C in MT-ND1, m.13650C>A, m.13674T>C, m.12705C>T and m.13263A>G in MT-ND5, of which there are no previous reports in the global literature." (PMID 38493220, 2024). "Other mRNAs were also less expressed in leprosy patients when compared to non-leprous samples, such as Bad, IL10, IL12 as well as several mitochondrial genes (mtCOX2, mtND1, mtND3 mtND5 mtATP6, and mtCYB)." (PMID 23798993, 2013).
melanoma (3 papers, 2024 to 2025). A malignant, usually aggressive tumor composed of atypical, neoplastic melanocytes. "Another study investigated the effects of truncating mutations in the mtDNA‐encoded complex I gene, Mt‐Nd5, in murine melanoma models, promoting a Warburg‐like metabolic shift that reshaped tumor microenvironments and elicited antitumor immune responses." (PMID 39494561, 2024). "We engineered truncating mutations of the mtDNA-encoded complex I gene, Mt-Nd5, into several murine models of melanoma." (PMID 38286828, 2024).
Nephropathy (3 papers, 2022 to 2024). A nonspecific term referring to disease or damage of the kidneys. "MT-ND5 mutation-associated nephropathy has shown a variable manifestation, either as focal segmental glomerular sclerosis (FSGS) or tubulo-interstitial disease." (PMID 39262552, 2024). "Moreover, nephropathy associated with MT-ND5 mutation has only been reported in nine cases so far." (PMID 39262552, 2024). "We confirmed the role of MT-ND5 and mitochondrial haplogroup H on renal disease (serum variables), and identified the MT-ND5-rs41535848G variant, along with mitochondrial haplogroup X, associated with higher risk of ESKD." (PMID 38858654, 2024).
Obesity (3 papers, 2021 to 2024). Accumulation of substantial excess body fat. "We assumed that MT-ND5 knockout mutant mice susceptible to obesity may be at risk of metabolic disorders." (PMID 39482535, 2024). "To assess the susceptibility to obesity, we fed a high-fat diet to mutant mice that did not exhibit the obese phenotype with MT-ND5 gene-knockdown mutations." (PMID 39482535, 2024).
osteosarcoma (3 papers, 2019 to 2022). A usually aggressive malignant bone-forming mesenchymal neoplasm, predominantly affecting adolescents and young adults. "This metabolic shift was reported in transmitochondrial osteosarcoma cybrids harboring the m.12418insA/MT-ND5 mutation." (PMID 32575796, 2020). "Control and LHON osteosarcoma 143B cybrids showed an increase in mtDNA amount and MT-CO1 and MT-ND5 mRNA levels after incubation in glucose-free/galactose 5 mM medium." (PMID 31226990, 2019).
diabetes (2 papers, 2022 to 2025). "According to recent publications, during the pathogenesis of diabetes, MT-ND4 has a quite low-expression pattern and on the contrary, MT-ND5 has a relevantly higher expression level, corresponding with the prediction expression level of their agonists individually." (PMID 35721855, 2022).
Hypertension (2 papers, 2023 to 2024). The presence of chronic increased pressure in the systemic arterial system. "Mutations in MT-ND5 have been associated with tubulo-interstitial kidney disease, clinically characterised by proteinuria and hypertension, which could partially explain its role in the overlap between CKD and CVD." (PMID 39258111, 2024).
pancreatic cancer (2 papers, 2021 to 2025). "Estimating the mitochondrial mutation rate in plasmatic extracellular vesicles from patients with pancreatic cancer showed an increased number of variants in MT-ND1, MT-CYB, and MT-ND5 genes in comparison with controls." (PMID 40943376, 2025).
adenoma (1 paper, 2018). A neoplasm arising from the epithelium. "It revealed that genes MT-CO1, MT-ND5 and three tRNAs (asparagine, cysteine and lysine) were reduced in adenomas." (PMID 30619609, 2018).
Aphasia (1 paper, 2020). An acquired language impairment of some or all of the abilities to produce or comprehend speech and to read or write. "Of some interest is the Wernicke’s aphasia in P5, with mutation m.12706 T > C in MT-ND5, which was characterized by a difficulty of understanding written and spoken language." (PMID 31996177, 2020).
atherosclerosis (1 paper, 2012). A disease characterized by the build-up of fatty material and calcium deposition in the arterial wall resulting in partial or complete occlusion of the arterial lumen. "Thus, it was demonstrated that at least five mitochondrial mutations occurring in MT-RNR1, MT-TL1, MT-ND2, MT-ND5, and MT-CYB genes are associated with atherosclerosis." (PMID 22997526, 2012).
craniopharyngioma (1 paper, 2021). A benign, partly cystic, epithelial tumor of the sellar region, presumably derived from Rathke pouch epithelium. "Lastly, m.12417CA>C, a LoF mutation in MT-ND5 was seen in a HGG, MB, and craniopharyngioma." (PMID 34337412, 2021).
gastric cancer (1 paper, 2018). A primary or metastatic malignant neoplasm involving the stomach. "The present study investigated the single nucleotide variants (SNVs) in mitochondrial DNA (mtDNA) of 13 paired gastric cancer tissue samples and seven gastric cancer cell lines using direct sequencing analysis of the MTND5 region." (PMID 33474396, 2018). "In the present study, we amplified the entire MTND5 gene from the total DNA in the gastric cancer cell lines and 13 gastric cancer tissue samples." (PMID 33474396, 2018). "The nucleotide at the same position of the MTND5 gene in the gastric cancer tissue sample 14 and the adjacent normal tissue was cytosine." (PMID 33474396, 2018).
gout (1 paper, 2018). A condition characterized by painful swelling of the joints, which is caused by deposition of urate crystals. "When we categorized mutant alleles according to their positions in the mitochondrial genomes, 45 mutant alleles in patients with gout were located in the MT-ND5 region, followed-by the MT-CYB region (41 mutant alleles; 1 mutant allele was located in the overlapping MT-ATP6 and MT-ATP8 region)." (PMID 29976239, 2018). "In the non-gout controls, the MT-CYB region contained 69 alleles, followed by the MT-ND5 region (67 alleles; 3 mutant alleles were located in the overlapping MT-ATP6 and MT-ATP8 region)." (PMID 29976239, 2018).
haemorrhagic stroke (1 paper, 2021). "Recently, it has been shown that MTND5 was downregulated in plasma blood mononuclear cells of a patient with haemorrhagic stroke after a single treatment of valproic acid (140 mg/kg)." (PMID 34416891, 2021).